MAPK4 (mitogen-activated protein kinase 4)
Diseases named in the same sentence as MAPK4 in open-access papers (continued):
Sharing a sentence is not in itself a finding about the gene and the disease.
gastric cancer (continued). "To investigate whether MAPK4 downregulation promotes gastric cancer metastasis by activating stromal cells, we examined whether MAPK4 knockdown affects the abundance of CAFs in orthotopic tumors of gastric cancer cells." (PMID 36797541, 2023). "In addition, miR-127 inhibits the proliferation and invasion of gastric cancer cells via Wnt7a, inhibits ovarian cancer cell proliferation by downregulating MAPK4, regulates the NF-κB pathway through TNFAIP3, and induces epithelial-mesenchymal transformation in lung cancer." (PMID 36371182, 2022). "Taken together, these results imply that the downregulation of MAPK4 in gastric cancer cells enhances MIF secretion to activate TAMs, which increases gastric cancer cell invasion and liver metastasis." (PMID 36797541, 2023). "In this coculture system, the downregulation of MIF in MAPK4-depleted BGC-823 cells not only robustly inhibited MIF secretion but also significantly suppressed Arg1 expression in BMDMs and gastric cancer cell invasion." (PMID 36797541, 2023). "In this study, we found that MAPK4 interacts with and phosphorylates MIF to promote its ubiquitination and degradation in gastric cancer cells." (PMID 36797541, 2023). "The downregulation of MAPK4 in gastric cancer cells increases MIF secretion to promote macrophage polarization, which facilitates gastric cancer liver metastasis." (PMID 36797541, 2023). "Furthermore, the ectopic expression of miR-433 and miR-127 in gastric cancer cell lines HGC-27 inhibits cell proliferation, cell cycle progression, cell migration and invasion by directly interacting with the mRNA encoding oncogenic factors KRAS and MAPK4 respectively." (PMID 23880861, 2013). "Because protumor TAMs in gastric cancer tissues typically exhibit high levels of CD206 expression, we tested whether MAPK4 knockdown affects CD206 expression in macrophages in an orthotopic tumor model." (PMID 36797541, 2023). "The results showed that gastric cancer tissues had significantly lower expression levels of MAPK4 than their matched adjacent nontumor tissues." (PMID 36797541, 2023). "Moreover, forced expression of MAPK4 in BGC-LM cells significantly inhibited macrophage activation and gastric cancer cell invasion in this coculture model." (PMID 36797541, 2023). "To investigate the clinical significance of MAPK4 in gastric cancer progression, we examined MAPK4 mRNA expression in paired tumor and nontumor tissues from gastric cancer patients by qRT-PCR." (PMID 36797541, 2023). "Quantitative RT‒PCR revealed that the MIF mRNA levels remained invariable regardless of the knockdown or ectopic expression of MAPK4 in gastric cancer cells." (PMID 36797541, 2023). "In this system, the depletion of MAPK4 in BGC-823 cells and MKN45 cells not only significantly enhanced the expression of arginase 1 (Arg1, a marker for activated TAM) and CD206 in BMDMs but also robustly promoted gastric cancer cell invasion." (PMID 36797541, 2023). "Moreover, we evaluated MAPK4 protein expression using a gastric cancer tissue array containing tumor tissues and paired nontumor tissues from gastric cancer patients." (PMID 36797541, 2023). "Moreover, we confirmed that MAPK4 expression was robustly decreased in BGC-LM cells compared with BGC-823 cells by western blotting, and this finding was verified by reduced MAPK4 expression in liver metastatic tissues compared with matched primary tumor tissues from gastric cancer patients." (PMID 36797541, 2023).
multiple myeloma (8 papers, 2019 to 2023). "Over-expression of miR-767-5p functions as a tumor drive through targeting MAPK4 in multiple myeloma." (PMID 32711558, 2020). "For example, it was reported that circRNA circ_0000190 inhibited the development of multiple myeloma by regulating miR-767-5p/MAPK4 pathway." (PMID 32264877, 2020). "MAPK4 was initially identified as a negative regulator of proliferation in noncancer cells such as preadipocytes and multiple myeloma cell lines." (PMID 36618768, 2022).
lung carcinoma (6 papers, 2017 to 2023). "In this study, the expression and function of MAPK4 were determined in cells of lung cancer, colon cancer and prostate cancer." (PMID 32711558, 2020). "further reported that MAPK4 overexpression could promote the progression of lung cancer, indicating MAPK4 is a potential target for lung cancer therapy." (PMID 33088477, 2020).
breast carcinoma (5 papers, 2021 to 2025). "Co-targeting AKT and PDK1 can therefore repress MAPK4-induced cancer cell growth, suggesting a potential therapeutic strategy to treat MAPK4-high cancers, including a large subset of "triple negative" breast cancer." (PMID 37531320, 2023). "For example, miR-515-5p, negatively regulated by LINC00673, is downregulated in breast cancer, and it exerts an anti-tumor effect by downregulating the MAPK4/Hippo signaling pathway." (PMID 33413401, 2021). "Specifically, MAPK4 is highly expressed in a large fraction of TNBC, which accounts for 15% to 20% of all breast cancer but with limited therapeutic options." (PMID 37531320, 2023).
ovarian carcinoma (5 papers, 2016 to 2026). A malignant neoplasm originating from the surface ovarian epithelium. "In osteosarcoma-derived U2OS and ovarian carcinoma-derived ES-2 cells, decreased MAPK4 mRNA translation mediates the prometastatic effect of IGF2BP1, suggesting that MAPK4 acts as a tumour suppressor." (PMID 36618768, 2022).
triple-negative breast carcinoma (4 papers, 2022 to 2025). An invasive breast carcinoma which is negative for expression of estrogen receptor (ER), progesterone receptor (PR), and human epidermal growth factor receptor 2 (HER2). "MAPK4 protein directly activates AKT, thereby promoting cell migration in triple-negative breast cancer." (PMID 38938027, 2024). "Here, using triple-negative breast cancer (TNBC) cell models, we demonstrate that MAPK4 can also enhance PDK1 protein synthesis, thus phosphorylate/activate PDK1 substrates beyond AKT." (PMID 37531320, 2023).
cervical cancer (3 papers, 2020 to 2025). A primary or metastatic malignant neoplasm involving the cervix. "Here we report that high MAPK4 expression is associated with significantly decreased overall survival rate in cervical cancer patient." (PMID 32711558, 2020). "Our results demonstrate for the first time that addition of PARP inhibitor may improve therapeutic outcome of MAPK4-deficient cervical cancer treated with radiation." (PMID 32711558, 2020). "Altogether, our data revealed that cervical cancer patients with high MAPK4 mRNA expression have lower survival rate." (PMID 32711558, 2020). "We found that MAPK4-knockout cervical cancer cells showed lower AKT phosphorylation level, and had heightened sensitivity to radiation treatment and PARP1 inhibitors." (PMID 32711558, 2020). "Colony formation, immunofluorescence and western blotting were used to examine the effects of MAPK4 knockout or over-expression on cervical cancer cells after radiation treatment." (PMID 32711558, 2020). "Our data in this study demonstrated that cervical cancer patients with high MAPK4 expression had lower survival probability and MAPK4 deletion blocked AKT phosphorylation in cervical cancer cells." (PMID 32711558, 2020). "The functional effects of MAPK4 knockout on the sensitivity of cervical cancer to radiation treatment and PARP1 inhibitors were further examined using xenograft tumor mouse models in vivo." (PMID 32711558, 2020). "Nevertheless, the functions of MAPK4 in radiation and its involvement in diseases, including cervical cancer, requires further investigation." (PMID 32711558, 2020). "After MAPK4-knockout cervical cancer cells were treated with 5 Gy irradiation, the markers for DNA double-chain breakage were detected by immunofluorescence." (PMID 32711558, 2020). "Cervical cancer cells were more sensitive to radiation treatment after MAPK4 knockout, as determined by colony formation, immunofluorescence and western blotting." (PMID 32711558, 2020). "To study the correlation between MAPK4 level and cervical cancer development, we determined the MAPK4 mRNA levels in cervical cancer tissues of different disease stages (n = 60)." (PMID 32711558, 2020). "We re-expressed MAPK4 using specific expressing plasmids in MAPK4 knockout cervical cancer cells, and examined the phosphorylation levels of AKT." (PMID 32711558, 2020). "MAPK4 is further found to affect the sensitivity of cervical cancer cells to PARP1 inhibitors by activating AKT phosphorylation." (PMID 32711558, 2020). "Our data in this study demonstrated that MAPK4 knockout could enhance the sensitivity of cervical cancer cells to radiation treatment both in vitro and in vivo, suggesting that targeting MAPK4 may be a promising radiosensitizer." (PMID 32711558, 2020). "However, little is known about the therapeutic efficacy of PARP inhibitors in the treatment of cervical cancer, either as a single agent or in combination with MAPK4 knockout." (PMID 32711558, 2020). "Together, these findings demonstrated that MAPK4 knockout could inhibit DNA repair and improve the sensitivity of cervical cancer to irradiation treatment and PARP1 inhibitors in vivo." (PMID 32711558, 2020). "Together, these results demonstrated that MAPK4 knockout alongside with PARP1 inhibition may improve the therapy of cervical cancer." (PMID 32711558, 2020). "Furthermore, the IC50 of PARP1 inhibitors was detected by re-expressing MAPK4 or over-expressing CA-AKT in MAPK4 knockout cervical cancer cells." (PMID 32711558, 2020). "Together, these data suggest that MAPK4 knockout could down-regulate cell proliferation, induce DNA damage and attenuate DNA repair in cervical cancer cells after irradiation treatment." (PMID 32711558, 2020). "However, the synergistic role of PARP1 inhibition in combination with MAPK4 intervention for cervical cancer therapy is yet to be elucidated." (PMID 32711558, 2020).
cervical cancer (continued). "In addition, p-AKT and γH2AX levels were determined in MAPK4-knockout cervical cancer cells that constitutively expressed AKT." (PMID 32711558, 2020). "Cervical cancer patients with high MAPK4 mRNA expression have lower survival rate." (PMID 32711558, 2020). "In addition, the phosphorylation levels of AKT were determined in MAPK4-overexpressing cervical cancer cells, which demonstrated an increase in phosphorylated AKT, but had no significant change in the levels of total AKT." (PMID 32711558, 2020). "In addition, MAPK4 knockout enhanced the sensitivity of cervical cancer cells to PARP1 inhibitors, olaparib and veliparib." (PMID 32711558, 2020). "Moreover, in vivo results demonstrated that MAPK4 knockout enhanced the sensitivity of cervical cancer to radiation and PARP1 inhibitors in mouse xenograft models." (PMID 32711558, 2020). "Thus, we then investigated the effect of MAPK4 knockout on the sensitivity of cervical cancer cells to PARP1 inhibitors, olaparib or veliparib." (PMID 32711558, 2020). "Furthermore, MAPK4 knockout was found to affect the sensitivity of cervical cancer cells to poly ADP-ribose polymerase 1 (PARP1) inhibitors by activating the phosphorylation of AKT." (PMID 32711558, 2020). "Moreover, MAPK4 knockout enhanced the sensitivity of cervical cancer to radiation and PARP1 inhibitors in mouse xenograft models." (PMID 32711558, 2020). "Because MAPK4 expression is associated with patient survival, these result suggest that MAPK4 may serve as a potential synergetic therapeutic target with PARP1 inhibitors in radiotherapy of cervical cancer." (PMID 32711558, 2020). "However, when analyzing the relationships between MAPK4 mRNA level and the survival of cervical cancer patients after chemoradiotherapy, it was found that the survival rate of cervical cancer patients in “MAPK4 High” group was lower than that of patients in “MAPK4 Low” group." (PMID 32711558, 2020). "Given that MAPK4 deletion enhanced the sensitivity of cervical cancer cells to radiation and PARP1 inhibitors, we next investigated the effect of MAPK4 deletion in vivo." (PMID 32711558, 2020). "Collectively, our data suggest that combined application of MAPK4 knockout and PARP1 inhibition can be used as therapeutic strategy in radiation treatment for advanced cervical carcinoma." (PMID 32711558, 2020). "Collectively, our data suggest that combined application of MAPK4 knockout and radiation treatment or PARP1 inhibition can be used as therapeutic strategy for advanced cervical carcinoma." (PMID 32711558, 2020). "In this study, we have not only demonstrated the suppressive role of MAPK4 knockout on AKT phosphorylation, but also identified the relationship between MAPK4 knockout and enhanced sensitivity of cervical cancer to radiation treatment and PARP1 inhibitors in cells and mouse models." (PMID 32711558, 2020). "The results showed that MAPK4 knockout itself did not significantly affect the colony formation of cervical cancer cells." (PMID 32711558, 2020). "To date, the regulatory mechanism of MAPK4 in cervical cancer remains unclear, and whether or not miR-767-5p and miR-127 could target MAPK4 and other potential transcriptional regulatory factors will require further investigation." (PMID 32711558, 2020).
cholangiocarcinoma (2 papers, 2020 to 2021). A carcinoma that arises from the intrahepatic biliary tree (intrahepatic cholangiocarcinoma) or from the junction, or adjacent to the junction, of the right and left hepatic ducts (hilar cholangiocarcinoma). "MAPK4 caused the activation of AKT independent of PI3K and PTEN, and levels of MAPK4 expression in obesity-related cancers such as endometrial and cholangiocarcinoma were extremely low, suggesting that this interaction requires further investigation." (PMID 32069845, 2020).
colorectal cancer (2 papers, 2019 to 2023). A primary or metastatic malignant neoplasm that affects the colon or rectum. "We also made similar observations on MAPK4 enhancing PDK1 protein levels in human non-small cell lung cancer H1299 and H157 cells, colorectal cancer HCT116 cells, and prostate cancer DU145 cells, suggesting the MAPK4-PDK1 axis beyond TNBC." (PMID 37531320, 2023).
diabetes (2 papers, 2016 to 2022). "More importantly, key genes of the respective pathways, such as AKT3, FGF2, FGF7, mitogen-activated protein kinase 4 (MAP3K4), MAP3K5, insulin receptor (INSR), AKT3, and mTOR, were also enriched in the analysis, thus explaining the link between diabetes and BCRL subjects in the present study." (PMID 36232660, 2022).
glioblastoma (2 papers, 2023 to 2025). The most malignant astrocytic tumor (WHO grade IV). "The viability and migration ability of MAPK4‐silenced glioblastoma multiforme (GBM) cells were evaluated using CCK8 and transwell assays, respectively, and cell cycle and apoptosis analyses were performed using flow cytometry." (PMID 36999945, 2023). "Additionally, the NF-κB pathway can exacerbate the Warburg effect, leading to increased expression of LINC01127, activation of the MAPK4-JNK pathway, and promotion of glioblastoma stem cells." (PMID 39988672, 2025).
lung adenoma (2 papers, 2016 to 2022). A benign, well circumscribed epithelial neoplasm that arises from the bronchus or the lung parenchyma. "Furthermore, the transcript levels of MAPK4 are upregulated by the oncogenic K-ras gene in lung adenomas." (PMID 36618768, 2022).
melanoma (2 papers, 2017 to 2023). A malignant, usually aggressive tumor composed of atypical, neoplastic melanocytes. "In the antigen presenting cells, (APC)/Cytokine/Chemokine/Immune category, differences in IL-2, IL-3 and STAT3 signaling pathways in melanoma and Wnt, Rho GTPases MAPK4/6 signaling pathways in HD mDC were observed." (PMID 37938561, 2023).
Obesity (2 papers, 2020 to 2021). Accumulation of substantial excess body fat. "MAPK4 is mitogen-activated protein kinase 4, which is involved in the absorption and decomposition of sugars and the formation of fat, so it is related to obesity traits." (PMID 34276758, 2021).
Sepsis (2 papers, 2020 to 2025). Sepsis is defined as life-threatening organ dysfunction caused by a dysregulated host response to infection. "At a log2FC>2 (adjusted P < 0.05) MAPK related genes F2rl1, Adm (marked as multi, as it was picked up for term searches “metabolic,” “hypoxia,” and “MAPK”), Mapk4, Gdf15, Dusp10, and Dusp8 were up-regulated in Isoflurane-Sepsis compared to only 2 genes in the Propofol-Sepsis group." (PMID 33392215, 2020).
adenoma (1 paper, 2024). A neoplasm arising from the epithelium. "USP8-mutated adenomas showed higher level of POMC, CDC25A, MAPK4 but lower level of CCND2, CDK6, CDKN1B than USP8-wild-type tumors." (PMID 38862897, 2024).
ameloblastoma (1 paper, 2022). The most common odontogenic tumor, arising from the epithelial component of the embryonic tooth and usually affecting the molar-ramus region of the mandible or maxilla. "Besides, “MAPK1/MAPK3 signaling” (R-HSA-5684996), “MAPK family signaling cascades” (R-HSA-5683057), “MAPK6/MAPK4 signaling” (R-HSA-5687128), and “MAPK cascade” (GO:0000165) were also dysregulated in ameloblastoma." (PMID 36160115, 2022).
autoimmune disease (1 paper, 2025). A disorder resulting from loss of function or tissue destruction of an organ or multiple organs, arising from humoral or cellular immune responses of the individual to their own tissue constituents. "This work lays the groundwork for the development of MAPK4-targeted treatments, offering a promising direction for improving RA management and advancing our understanding of autoimmune disease mechanisms." (PMID 39863600, 2025). "In summary, this study reveals the diverse roles of MAPK4 in regulating of B cell functions, with potential implications for developing therapeutic strategies for RA and related autoimmune diseases." (PMID 39863600, 2025). "Our study contributes novel insights into the role of MAPK4 in B cell regulation and its implications for autoimmune diseases such as RA." (PMID 39863600, 2025). "This will further consolidate MAPK4 as a true therapeutic target and an understanding of B cell biology and its perturbation in autoimmune diseases." (PMID 39863600, 2025). "While earlier research has often highlighted the positive regulatory mechanisms of MAPK4 in various signaling pathways, our results suggest a complex, context-dependent regulation of immune responses by MAPK4, particularly in the setting of autoimmune diseases like RA." (PMID 39863600, 2025). "In summary, the results of this study suggest that MAPK4 plays various roles in the regulation of B cell function, with potential implications for the development of therapeutic strategies targeting RA and related autoimmune diseases." (PMID 39863600, 2025).
autoimmune hepatitis (1 paper, 2023). Hepatitis caused by autoantibodies. "Inhibition of MAPK4 ameliorated the activation of CD4+ T cells in mice with autoimmune hepatitis." (PMID 36999945, 2023).
brain tumors (1 paper, 2020). "In vivo tumorigenicity monitored by In-Vivo FX Pro system every 5 days showed that downregulation of circ-MAPK4 significantly inhibited formation of xenograft brain tumors (activity of fluorescence, p < 0.05)." (PMID 31992303, 2020).
cleft lip/palate (1 paper, 2020). Cleft lip and palate is a fissure type embryopathy extending across the upper lip, nasal base, alveolar ridge and the hard and soft palate. "Presently, the literature review reveals no study on the association between the MAPK4 & SOX1-OTgene polymorphisms and the risk of developing non-syndromic cleft lip and/or palate NSCL/P in the Indian population." (PMID 32908649, 2020).